RN7SKP240 (RN7SK pseudogene 240)
Gene: Miscellaneous RNA gene on chromosome 6 (22,085,544 to 22,085,918, forward strand). Ensembl gene ENSG00000222515.
Homologues: Orthologues: chimpanzee 7SK (98% identical). Paralogues in human: RN7SKP77 (65% identical), RN7SKP90 (63% identical), RN7SKP79 (63% identical), RN7SKP133 (63% identical), RN7SKP180 (62% identical), RN7SKP189 (62% identical), RN7SKP146 (62% identical), RN7SKP250 (62% identical), RN7SKP124 (61% identical), RN7SKP170 (61% identical), RN7SKP177 (61% identical), RN7SKP203 (61% identical), and 284 more.